CDX2 (caudal type homeobox 2)
Diseases named in the same sentence as CDX2 in open-access papers (continued):
Sharing a sentence is not in itself a finding about the gene and the disease.
ascending colon cancer (1 paper, 2023). A malignant neoplasm involving the ascending colon. "Endoscopic biopsy revealed adenocarcinoma, and IHC showed the ascending colon cancer had the same expression pattern of CK7, CK20, and CDX2 as the cutaneous tumor." (PMID 37962682, 2023).
autoimmune thyroiditis (1 paper, 2019). "Another functional polymorphism of the VDR gene, rs11568820 (Cdx2), has been shown to influence the immune system, although it has not been studied for its association with autoimmune thyroiditis to date." (PMID 31531369, 2019).
Barrett adenocarcinoma (1 paper, 2021). An adenocarcinoma arising from Barrett metaplastic epithelium in the esophagus. "In Barrett's adenocarcinoma, ectopic CDX2 expression in mice seemed sufficient to induce a tissular differentiation change and cause metaplasia but insufficient to cause degeneration into cancer." (PMID 34563241, 2021). "In Barrett's adenocarcinoma, some authors suggested that variations in CDX2 promoter methylation induced by chronic inflammation may guide intestinal differentiation." (PMID 34563241, 2021).
bile reflux (1 paper, 2023). "Previous evidence has revealed that caudal type homeobox 2 (CDX2), SRY-related HMG box-2 (SOX2), and farnesoid X receptor (FXR) are involved in the bile reflux-induced GIM." (PMID 37206332, 2023).
bladder cancers (1 paper, 2023). "Differential CDX2 expression has been reported in different subtypes of bladder cancer." (PMID 37627900, 2023). "The CDX2 could be a useful biomarker to distinguish some subtypes of bladder cancers that have difficulty in differential diagnosis due to their shared morphologic resemblance." (PMID 37627900, 2023).
caudal regression syndrome (1 paper, 2022). "We propose CDX2 variants as rare genetic cause for a multiple congenital anomaly syndrome that can include features of caudal regression syndrome and VACTERL." (PMID 34671974, 2022). "The CDX2‐associated clinical phenotype overlaps with caudal regression syndrome, which encompasses a range of congenital defects." (PMID 34671974, 2022).
cecal adenocarcinoma (1 paper, 2011). "CDX2's positive nature in the prostate specimens, as well as the original bowel specimens from this case, strongly correlate with a diagnosis of metastatic spread from the original cecal adenocarcinoma to the prostate." (PMID 21689464, 2011).
celiac disease (1 paper, 2020). An autoimmune genetic disorder with an unknown pattern of inheritance that primarily affects the digestive tract. "A CK7−/CK20+/CDX2+/SATB2+ pattern profile was present in three Crohn’s disease-associated SBAs, six Spo-SBAs and five celiac disease associated-SBAs." (PMID 33228145, 2020). "Among them, there were two celiac disease-associated SBAs and four Spo-SBAs; worthy of note, none of the three Crohn’s disease-associated SBAs having a CK7−/CK20+/CDX2+/SATB2+ pattern expressed AMACR." (PMID 33228145, 2020).
chronic pancreatitis (1 paper, 2014). A chronic inflammatory process causing damage and fibrosis of the pancreatic parenchyma. "We reported that CDX2 expression is weak and heterogeneous is all normal pancreas and chronic pancreatitis." (PMID 24489794, 2014). "CDX2 expression in normal pancreas, chronic pancreatitis, PanIN and PDAC." (PMID 24489794, 2014). "Interestingly, chronic pancreatitis has similar CDX2 expression pattern to normal pancreas." (PMID 24489794, 2014). "Interestingly, chronic pancreatitis had similar CDX2 staining pattern to normal pancreas." (PMID 24489794, 2014). "In summary, we, in this study, systemically and extensively investigated the expression and role of CDX2 in PDAC with comparison to normal pancreas and chronic pancreatitis." (PMID 24489794, 2014). "CDX2 expression levels were evaluated by immunohistochemical analysis in normal pancreas and chronic pancreatitis resected with no history or evidence of PDACs." (PMID 24489794, 2014). "Therefore, we set up to investigate the CDX2 expression in PDAC as well as it precursor lesions–PanIN, with comparison to normal pancreas and chronic pancreatitis." (PMID 24489794, 2014).
Cirrhosis (1 paper, 2023). A chronic disorder of the liver in which liver tissue becomes scarred and is partially replaced by regenerative nodules and fibrotic tissue resulting in loss of liver function. "Among the multiple biomarkers included in the analyses (tumor size, age, tumor number, tumor differentiation, tumor size, presence of cirrhosis, CDX2, CK19, CK7, pCEA, mCEA, CA19-9), only CK7 and the presence of immune cell infiltrates were correlated with OS (p = 0.016, p = 0.0028)." (PMID 37174934, 2023).
cleft palate (1 paper, 2021). Cleft palate is a fissure type embryopathy that affects the soft and hard palate to varying degrees. "This comprehensive analysis revealed decreases in gene expressions associated with lung development; Foxa2, Notch1, Foxp2, Nkx2.1, and intestine development; Cdx2, Foxf2, Foxl1, and skeletal development; Hoxd12, Hoxd13, Scx, Brachyury, and cleft palate; Foxf2." (PMID 34671097, 2021).
Crohn disease (1 paper, 2020). A gastrointestinal disorder characterized by chronic inflammation involving all layers of the intestinal wall, noncaseating granulomas affecting the intestinal wall and regional lymph nodes, and transmural fibrosis. "In addition, the intestinal differentiation transcription factor CDX2 has been reported to be more frequently negative in Crohn’s disease-associated SBAs in comparison with celiac or Spo-SBAs." (PMID 33228145, 2020).
cystadenoma (1 paper, 2019). A benign or borderline cystic epithelial neoplasm arising from the glandular epithelium. "Mucinous cystadenomas showed more heterogeneous results, in which 71.8% (28/39) and 35.9% (14/39) were expressing CK7 and PAX8, respectively, while 10.3% (4/39) were positive for CK20 and CDX2." (PMID 31771640, 2019).
cystic teratoma (1 paper, 2022). "Lastly, expression of CK20, CDX2, and CK7 corroborates clinically in our patient with a PMP-derived ruptured appendiceal mucinous-like tumor arising from a secondary origin, a malignant transformed ovarian mature cystic teratoma." (PMID 35272690, 2022).
dental caries (1 paper, 2021). The decay of a tooth, in which it becomes softened, discolored, and/or porous. "A number of studies on the associations of VDR gene polymorphisms, such as FokI, ApaI, BsmI, Cdx2, and TaqI, with the susceptibility to dental caries were published, and the TaqI (rs731236 T>C) polymorphism was the most studied variant." (PMID 33960841, 2021).
depression (1 paper, 2014). "Another major finding here is that VDR variants ApaI (AA) and Cdx2 (AA) interacted with dietary vitamin D to modify likelihood of depression." (PMID 24699387, 2014).
duodenal adenocarcinoma (1 paper, 2013). A carcinoma that arises from glandular epithelial cells of the duodenum. "Histological subtype and immunohistochemical staining pattern for CK7, CK20 and CDX2 were assessed for n = 198 cases of pancreatic ductal, distal bile duct, ampullary and duodenal adenocarcinoma with clinical follow-up." (PMID 24053229, 2013).
endometrial tumour (1 paper, 2015). "Immunohistochemistry, as well, confirmed a primary endometrial tumour with negativity for GCDFP-15, CEA, CDX2, CK20; and positivity for CK7, ER, and Vimentin." (PMID 26682077, 2015).
enterocolitis (1 paper, 2012). An inflammatory process affecting the small intestine and colon. "Whereas, the reduced expression of cdx-1 and cdx-2 genes were associated with the development of enterocolitis in intestinal mucosa." (PMID 22824143, 2012).
epithelial colon tumors (1 paper, 2017). "As a result, we examined in detail the impact of FOXA factors on enhancer regions at the CDH1, CDX2 and EPHB3 genes which are among the signature genes of epithelial colon tumors and which are downregulated in Snail1-expressing LS174T cells." (PMID 29155818, 2017).
esophageal SCC (1 paper, 2019). "In the previous report, esophageal SCC consistently expressed CK5/6 (in 98% of all cases) and p63 (100%) with strong reactivity, partially expressed CK7 (34%) and CDX2 (27%), but most of CK7 and CDX2 expression demonstrated weak reactivity." (PMID 30890174, 2019).
esophageal ulcer (1 paper, 2009). An ulcerated lesion in the esophageal wall. "Aberrant and inconsistent Cdx2 nuclear expression was seen in the proliferative compartment of the squamous mucosa, close to esophageal ulcers and/or hyperplastic lesions (Group A = 4/22 [18.2%]; Group B = 6/22 [27.3%]; Group C = 8/20 [40.0%])." (PMID 19664209, 2009). "Cdx2 was never expressed in native squamous epithelia (including any non-ulcerative esophagitis) in the upper third of the esophagus." (PMID 19664209, 2009). "These hypotheses are further supported by the finding that no Cdx2 expression was detected in squamous epithelia (far from esophageal ulcers/metaplastic changes), nor in any of the 4 cases of SCC." (PMID 19664209, 2009).
Familial adenomatous polyposis (1 paper, 2023). Familial adenomatous polyposis (FAP) is characterized by the development of hundreds to thousands of adenomas in the rectum and colon during the second decade of life. "Commensurate reductions in FXR and CDX2 resulting from inactivating APC mutations are observed in the tumor tissues of Apcmin/+ mice and familial adenomatous polyposis (FAP) patients, indicating that mutations in CRC-related genes also contribute to intestinal FXR gene silencing." (PMID 38203175, 2023).
folate deficiency (1 paper, 2019). A nutritional condition produced by a deficiency of FOLIC ACID in the diet. "Using ChIP-seq and RNA-seq assays, we demonstrated that an increase in H2AK119ub1 level downregulated the expression of the NTC-related genes Cdx2, Nes, Pax6, and Gata4 in mESCs under conditions of folate deficiency." (PMID 31722724, 2019).
gallbladder adenoma (1 paper, 2024). A polypoid epithelial neoplasm that arises from the gallbladder. "Recent research has showed the significance of CDX2 (homeobox domain–containing transcription factor) in not only intestinal inflammation but also in the development of tumors making CDX2 as a noteworthy marker for gallbladder adenoma." (PMID 39493791, 2024).
gastric adenoma (1 paper, 2021). A neoplastic polyp that arises from the stomach. "Intestinal-type gastric adenomas show MUC2 and/or CDX2 expression, whereas the foveolar type is characterized by strong/diffuse MUC5AC positivity, weak/focal MUC6 immunostaining, and an absence of MUC2 or CDX2 expression." (PMID 34206291, 2021).
goblet-cell adenocarcinoma (1 paper, 2024). "Immunohistochemical testing was performed using synaptophysin, chromogranin A, neuronal specific enolase, CD56, CDX-2, CK20, CEA, MUC2 and Ki67, thus establishing the final diagnosis of high-grade extra-appendiceal goblet-cell adenocarcinoma of the cecum, G3." (PMID 40729214, 2024).
hereditary non-polyposis colorectal cancers (1 paper, 1999). "To clarify the role of CDX2 in colorectal carcinogenesis, we determined its genomic structure, and searched for mutations of CDX2 in 49 sporadic colorectal carcinomas and ten hereditary non-polyposis colorectal cancers (HNPCC) without microsatellite instability." (PMID 10027310, 1999).
Hyperglycemia (1 paper, 2021). An increased concentration of glucose in the blood. "After CDX2 overexpression and knockdown of CFTR under HG conditions, CDX2 cannot present the suppression of Wnt/β-catenin signaling to inhibit hyperglycemia-associated renal tubular lesions." (PMID 33621200, 2021). "CDX2 inhibited the increase of activated β-catenin and Snail to suppress hyperglycemia-associated RTECs injury and renal tubular-interstitial fibrosis, and it’s effects may rely on CFTR upregulation." (PMID 33621200, 2021). "CDX2 upregulated E-cadherin and suppressed partial epithelial-mesenchymal transition (EMT), which can alleviate hyperglycemia-associated RTECs injury." (PMID 33621200, 2021). "These evidences revealed that CDX2 interfered with β-catenin activation by positively regulating CFTR, ultimately inhibiting hyperglycemia-associated renal tubular lesions." (PMID 33621200, 2021). "Immunofluorescence micrographs showed thatCDX2 overexpression alleviates hyperglycemia-induced RTECs damage, and CDX2 knockdown induces the damages, and overexpression of CDX2 in vivo can alleviate glomerular damage and renal tubular lesions during DKD." (PMID 33621200, 2021).
IgA nephropathy (1 paper, 2021). "In the kidney tissue of T1D, T2D mice and DKD patients, CDX2 was decreased at the transcription and protein levels in kidney tissues, and kidney CDX2 is downregulated in IgA nephropathy and in UUO." (PMID 33621200, 2021). "kidney CDX2 is downregulated in IgA nephropathy and in UUO (unilateral ureteral obstruction)." (PMID 33621200, 2021).
infectious colitis (1 paper, 2021). A viral or bacterial infectious process affecting the large intestine. "Since DCLK1 was significantly overexpressed in Rag-1−/− mice in response to CR infection, we further bred DCLK1fl/fl;CDX2-Cre/ERT2 mice with Rag1−/− to generate double knockout (DKO) mice to see whether the DKOs are more susceptible to infectious colitis." (PMID 34226497, 2021).
leukocytosis (1 paper, 2020). "White blood cell (WBC) counts of LysM:Cdx2 mice showed progressive leukocytosis and myeloid skewing with age." (PMID 32541670, 2020). "Conversely, when Cdx2 expression is restricted to myeloid cells in LysM:Cdx2 mice, there is a more homogeneous phenotype, typified by myelocytic expansion, leukocytosis, and splenomegaly, but without the thrombocytopenia that is hallmark to Scl:Cdx2 mice." (PMID 32541670, 2020).
mesonephric neoplasm (1 paper, 2025). An epithelial neoplasm of the female reproductive system arising from mesonephric remnants. "Most tumors were positive for cytokeratin-7 (8/9), EMA (9/9), estrogen and progesterone receptor (9/9), CD10 (7/9, including a luminal pattern reminiscent of mesonephric neoplasms), nuclear β-catenin (8/9), and CDX2 (8/9)." (PMID 38418687, 2025).
mesothelioma (1 paper, 2023). A usually malignant and aggressive neoplasm of the mesothelium which is often associated with exposure to asbestos. "Similarly, CEA, CK7, CK20, TTF1, and CDX2 are usually positive in adenocarcinoma cells, while WT-1, calretinin, D2-40, CK5/6, and cytokeratin are often positively expressed in mesothelioma cells." (PMID 37359022, 2023).
mucinous adenocarcinoma of the appendix (1 paper, 2016). Mucinous adenocarcinoma of the appendix is a very rare, slow growing, well-differentiated epithelial neoplasm of the appendix characterized by abundant mucin production. "While the molecular mechanisms of mucinous adenocarcinomas of the appendix remain poorly understood, previous studies have shown positive reactivity for CK20, CDX2 and MUC2 in these tumours." (PMID 27982068, 2016).
mucinous cystadenocarcinoma (1 paper, 2024). An invasive adenocarcinoma characterized by cystic changes and the presence of malignant glandular cells which contain intracytoplasmic mucin. "In that case of a 52-year-old male, the neoplasm demonstrated CK7-positive, CK20-positive, CDX2-negative ovarian-type mucinous cystadenocarcinoma." (PMID 39036214, 2024).
mucinous lung adenocarcinomas (1 paper, 2025). "Vice versa, enteric type and mucinous lung adenocarcinomas frequently show expression of CDX2 and CK20, often also without TTF-1 and Napsin A expression." (PMID 40564811, 2025).
myeloid malignancies (1 paper, 2021). "To date, this is the only study describing a role for KDM3A in myeloid malignancies; further investigation is therefore required to corroborate the significance of KDM3A-mediated CDX2 overexpression in this context or to reveal additional pathophysiological roles for KDM3A." (PMID 34944554, 2021).
myeloproliferative neoplasm (1 paper, 2020). A clonal hematopoietic stem cell disorder, characterized by proliferation in the bone marrow of one or more of the myeloid (i.e., granulocytic, erythroid, megakaryocytic, and mast cell) lineages. "After tamoxifen induction of Cre-recombinase, Scl:Cdx2 mice developed a variety of hematological diseases including MDS, myeloproliferative neoplasm (MPN) and AL." (PMID 32541670, 2020).
myopia (1 paper, 2025). "Additionally, regulatory transcriptional factors, such as Cdx2 in the small intestines and Atf4 in the liver — both are involved in hypoxia pathway — were activated in myopia." (PMID 41330940, 2025).
olfactory neuroblastoma (1 paper, 2022). An olfactory neuroblastoma arising in the paranasal sinus. "This is the first study reporting the immunohistochemical expression profile of SATB2, GATA3, and CDX2 in olfactory neuroblastoma (ONB)." (PMID 35522392, 2022).
ovarian endometrioid adenocarcinoma (1 paper, 2017). An endometrioid adenocarcinoma arising from the ovary. "Primary ovarian endometrioid adenocarcinomas almost always exhibit diffuse positivity for CK7 and CA 125, while CK20, carcinoembryonic antigen (CEA), and CDX2 are usually negative; the converse immunophenotype (CK20+, CEA+, CDX2+, CK7−, and CA 125−) is observed in mCRC." (PMID 28730323, 2017).
pancreatic diseases (1 paper, 2014). "Our findings provide a better understanding on CDX2 in pancreatic diseases and are practically useful." (PMID 24489794, 2014). "Our study clearly demonstrates CDX2 expression in pancreatic diseases including PDAC, which is practically important when CDX2 is used to establish the primary sites of adenocarcinomas of unknown origin." (PMID 24489794, 2014).
papillary adenocarcinoma (1 paper, 2025). A morphologic variant of adenocarcinoma. "The mixed gastric-intestinal type intramucosal papillary adenocarcinoma displayed immunopositivity for MUC2, villin, and CDX2, consistent with features of intestinal differentiation." (PMID 41404072, 2025).
Parkinson disease (1 paper, 2019). A progressive degenerative disorder of the central nervous system characterized by loss of dopamine producing neurons in the substantia nigra and the presence of Lewy bodies in the substantia nigra and locus coeruleus. "In a randomized double blind control trial of patients with Parkinson disease (PD), the effect of vitamin D3 (1200 IU/day for 12 months) to stabilize PD were only associated with the VDR FokI TT or CT but not the other SNPs examined (i.e., BsmI, Cdx2, ApaI and TaqI)." (PMID 31167402, 2019).
prostate acinar adenocarcinomas (1 paper, 2023). "Recently, a small proportion of prostate acinar adenocarcinomas have been found to contain CDX2, a marker of intestinal epithelial cell development that is expressed in most primary and metastatic colorectal adenocarcinomas." (PMID 37185408, 2023).
pseudomyxoma peritonei (1 paper, 2023). An appendix cancer that is characterized by progressive accumulation of mucus-secreting tumor cells within the abdomen and pelvis. "AGN343 patient had a pseudomyxoma peritonei (CK7 − /CK20 score 3 + /CDX2 score 3/SABT2 score 1, and ER − /PAX8 − /WT1 −); she underwent right and transversal colectomy during debulking, but neither primary cancers nor polyps were identified." (PMID 36346458, 2023).
pulmonary tuberculosis (1 paper, 2018). A bacterial infection that affects the lungs and is caused by Mycobacterium tuberculosis. "In the same population, the promoter polymorphisms Cdx2 G/A and A1012G revealed that genotype “GG” of Cdx2 associated with protection and haplotype A-A (A allele of Cdx-2 and A allele of A1012G) with susceptibility to pulmonary tuberculosis." (PMID 30167433, 2018).
renal fibrosis (1 paper, 2021). A final common manifestation of a wide variety of chronic kidney diseases characterized by glomerulosclerosis and tubulointerstitial fibrosis. "Meanwhile, renal CDX2 amounts were negatively correlated with the degree of renal fibrosis." (PMID 33621200, 2021). "In vivo, overexpression CDX2 improved renal function and renal fibrosis in T1D." (PMID 33621200, 2021).